TFEB (transcription factor EB)
Diseases named in the same sentence as TFEB in open-access papers (continued):
Sharing a sentence is not in itself a finding about the gene and the disease.
tumor (continued). "Notably, however, the effect of this co‐occurrence on cancer cell survival depends on the tissue in which both mTORC1 and TFEB are hyperactive; for example, TFEB‐mTORC1 hyperactivity can allow tumour‐associated macrophages to outcompete cancer cells." (PMID 37728021, 2023). "Third, TFEB depletion reduces tumor formation in TSC-deficient xenografts." (PMID 37627070, 2023). "Moreover, upregulation of HPA in GC is significantly linked to advanced tumor stage, while increased TFEB expression in GC tissues is correlated with poor prognosis." (PMID 35970822, 2022). "Therefore, exploring anticancer strategies underlying regulation of TFEB should be based on distinct tumor types." (PMID 34490237, 2021). "Thus, elucidating the roles of TFEB in tumor cells and tumor-associated macrophages is important." (PMID 38287113, 2024). "However, studies found that excessive induction of TFEB is linked with carcinogenic risk, suggesting that TFEB may regulate tumor genesis." (PMID 35851059, 2022). "TFEB was associated with tumorigenesis and its elevated expression could promote autophagy and lysosomal biogenesis activating related signaling pathways to control cell proliferation and tumor survival and progression." (PMID 35597916, 2022). "However, it emphasized on TFEB-mediated mitochondrial regulation and the association between Drp-1 and mTOR, thus ignoring the positive effect of Lut in inhibiting Dox-induced cardiotoxicity in cardiomyocytes and tumor cells." (PMID 34722681, 2021). "In this context, researchers have identified a novel transcriptional mechanism that regulates ATP7B expression in drug-resistant tumor cells through Pt-dependent transcription factor EB (TFEB) activation." (PMID 40406488, 2025). "In colorectal cancer, metabolic enzymes such as SHMT2, LDHB, and TFEB are selectively targeted through acetylation-dependent degradation or stabilization, reflecting the metabolic vulnerability of this tumor type." (PMID 41213956, 2025). "Alleviation of these effects by systemic depletion of CD8+ T cells further supports the critical role of p-STAT3/HLF/TFEB transactivation–regulated PD-L1 expression in tumor immunogenicity." (PMID 40779629, 2025). "This study provides novel insights into the mechanisms of TFEB regulation and its potential therapeutic implications for tumor adaptive progression." (PMID 40958774, 2025). "As a result, elevated lysosomal system activity is commonly observed in tumor cells, making TFEB an attractive target for cancer treatment." (PMID 40083935, 2025). "ELDA (extreme limiting dilution analysis) analysis demonstrated that TFEB KD cells had an ∼10-fold lower tumor-initiating cell frequency compared with control cells." (PMID 39814550, 2025). "Zoledronate reduced lysosomal acidification by inhibiting isoprene modification of Rab family proteins, enhanced tumor antigen cross-presentation and activated the TFEB pathway." (PMID 39776793, 2025). "Our analysis of the TCGA database similarly revealed that in LUAD, TFEB expression is lower in tumor tissues compared to normal tissues, and low TFEB expression correlates with poor survival outcomes." (PMID 40083935, 2025). "TFEB activation promotes lysosomal function and autophagic flux, thereby facilitating tumor cell growth and metastasis." (PMID 40858538, 2025). "Upregulation of epigenetic and transcriptional regulators such as NPM1, SMARCA4, ASPSCR1-TFE3 and TFEB further suggests that tumor signals drive transcriptional reprogramming of model immune cells, creating a stable pro-oncogenic phenotype." (PMID 41514627, 2025). "This was further validated in GBC samples from patients, where tumor HLF and TFEB expression levels were associated with the response to anti–PD-L1 treatment." (PMID 40779629, 2025). "The upregulation of catabolic processes mediated by TFEB allows tumorigenesis, and it is involved in the alterations of the tumor microenvironment." (PMID 39000232, 2024).
tumor (continued). "Induction of the Krebs cycle-derived metabolite itaconate in cancer cells facilitates TFEB-mediated antigen presentation and anti-tumor immunity." (PMID 39349845, 2024). "Taken together, these results suggested that the itaconate induced tumor immunogenicity by upregulating antigen presentation via TFEB." (PMID 39349845, 2024). "While the specific regulatory functions of TFEB in tumor angiogenesis remain under investigation, research conducted on embryos and newborn mice suggests that TFEB plays a role in the vascular development of endothelial cells (ECs)." (PMID 39000232, 2024). "TFEB has been reported to be able to control cellular metabolic patterns and promotes tumour progression by inducing autophagy." (PMID 38938061, 2024). "In our clinical data, we found that the high level of TFEB correlated with bigger tumour size, which also implies its promising clinical therapeutic application." (PMID 38938061, 2024). "TFEB-altered tumours, consisting of TFEB-translocated and amplified tumours, differing in their biological behaviour, are rare entities and even more so in the setting of solid organ transplantation." (PMID 37415400, 2024). "And it has been demonstrated that the inhibition of lysosome function by PDCD4 depends on TFEB, and in the TME, PDCD4 deficiency can promote the anti-tumor effect of macrophages by enhancing TFEB expression." (PMID 38370407, 2024). "Here, we report a rare example of metastatic TFEB-translocated tumour in a kidney transplant patient." (PMID 37415400, 2024). "This also reconciles FLCN's paradoxical role as a tumour suppressor, specifically by limiting the extent of TFEB-driven oncogenic transcriptional programs." (PMID 38994736, 2024). "Mechanistically, itaconate upregulates TFEB-mediated antigen presentation and subsequently elevates tumor immunogenicity, which is attenuated by TFEB knockdown." (PMID 39349845, 2024). "Our study demonstrated that itaconate upregulates TFEB-mediated antigen presentation to enhance tumor immunogenicity." (PMID 39349845, 2024). "Subsequently, TRIM25 promotes the nuclear translocation of TFEB and transcription of autophagy-related genes by increasing its K63-polyubiquitination, thereby reducing tumor sensitivity to PTX." (PMID 38926803, 2024). "Equally, does AMPK contribute (i.e., by phosphorylation of FNIP1) to the pro-tumour effects of TFEB in certain malignancies?" (PMID 38994736, 2024). "We have also developed a model for a TFEB translocation, MALAT1-TFEB, where TG lines were created from both the primary tumor and a lymph node metastasis." (PMID 38386415, 2024). "The results showed that the ability of TFEB knockdown cells to form tumours in nude mice was significantly reduced, and their tumorigenesis rate and size were significantly lower than those in the control group." (PMID 38938061, 2024). "The phosphorylation of the key transcription factor STAT3, serving as a target of the IL‐6 receptor beta (glycoprotein 130, gp130) or TFEB in macrophages, mediated M2 polarization and promoted tumor cell proliferation and migration." (PMID 36794651, 2023). "Curcumin can regulate the functions of lysosomes to exert anti-tumor activity by directly binding to TFEB and increasing the nuclear translocation and transcriptional activity of TFEB." (PMID 37484013, 2023). "By contrast, it seems likely that the ability of amplified or hyperactive TFEB to promote the growth of established tumours is partly downstream of macro‐autophagy induction, which enables pro‐survival shifts in metabolism." (PMID 37728021, 2023). "Loss of FLCN in DCs selectively impairs cDC1 function in vivo in a TFEB-dependent manner and phenocopies SLC38A2 deficiency by eliminating the anti-tumour therapeutic effect of glutamine supplementation." (PMID 37407815, 2023). "We found that tumors were significantly smaller in MIAshTFEB, than MIAshNT cells, indicating that TFEB contributes to PDAC tumor growth." (PMID 36746928, 2023).
tumor (continued). "In turn, TFEB hyperactivity promotes renal cell proliferation and increases tumour volume, likely through concurrent induction of mTOR activity and ATG transcription." (PMID 37728021, 2023). "This suggests that TFEB drives tumorigenesis despite inducing the otherwise tumour‐suppressive macro‐autophagy programme." (PMID 37728021, 2023). "As such, the effects of TFEB‐mediated upregulation of ATGs depend acutely on the stage of tumour progression." (PMID 37728021, 2023). "TFEB rearranged RCC is a separate entity classified by the 2016 WHO Classification of Tumors of the Urinary System as a subtype of the microphthalmia transcription factor (MiT) family of tumors, which also includes the more common Xp11 rearranged RCC." (PMID 36830782, 2023). "Cisplatin treatment induced TFEB nuclear translocation, increasing the expression of programmed cell death-ligands 1 and 2 (PD-L1 and PD-L2) to foster an immunosuppressive tumor microenvironment that mediates immune evasion and drug resistance." (PMID 37445831, 2023). "In this context, our findings shed light on a new transcription mechanism that regulates ATP7B expression in resistant tumor cells through Pt-dependent activation of TFEB." (PMID 35053335, 2022). "Deficient SPOP contributes to accumulated CHAF1A proteins, thereby sustaining tumor autophagy via induction of TFEB." (PMID 35773729, 2022). "Down-regulated or DLBCL-associated SPOP mutations contribute to CHAF1A accumulations, thereby enhancing tumor autophagy of DLBCL in a TFEB-dependent manner." (PMID 35773729, 2022). "It is highly likely that TFEB-mediated transactivation of ATP7B is used as a Pt defense mechanism by different tumor cells." (PMID 35053335, 2022). "Taken together, SPOP/CHAF1A axis restricts tumor autophagy in a TFEB-dependent manner, and targeting TFEB-mediated signaling represents a useful strategy for SPOP-deficient DLBCL." (PMID 35773729, 2022). "As a tumor suppressor, the global autophagy regulator TFEB is required to regulate IDH1/2 expression and induces myeloid differentiation by controlling IDH1/2-TET axis." (PMID 35526025, 2022). "This poses a question, namely, what are the mechanisms that allow Pt to modulate TFEB activity in tumor cells?" (PMID 35053335, 2022). "HIF-1/ERR connection can accelerate tumor cell tolerance to hypoxia and improve metabolism, whereas TFEB-ERR axis-induced lipid reprogramming improves membrane fluidity and promotes cell invasion." (PMID 36072980, 2022). "Correspondingly, TFEB suppression results in reduced ATP7B expression and elevated susceptibility of tumor cells to cisplatin." (PMID 35053335, 2022). "Our study illustrates the important role of TFEB in regulating the tumor immune microenvironment in OC." (PMID 34091590, 2021). "TFEB inhibits STAT3 activation, thus suppressing the production of an array of tumor-associated macrophage effector molecules and blocking the transcription of PPARγ, inhibiting the downstream expression of proinflammatory cytokines and HIF1α." (PMID 33912071, 2021). "Because of the important role of the TFEB/PD-L1 and MHC axis in regulating the tumor microenvironment with chemotherapy, TFEB is expected to become a good biomarker for immunotherapy." (PMID 34091590, 2021). "This study suggests that it is necessary to monitor the sensitivity of the tumor to sunitinib in some mRCC patients with high expression of TFE3 or TFEB." (PMID 33637706, 2021). "The mechanism underlying these tumor-suppressive activities of miR-29-3p involves the downregulation of autophagy-related 9A (ATG9A) and transcription factor EB (TFEB), which control the trafficking of autophagosome and lysosomal function." (PMID 33435156, 2021). "CDDP treatment induced TFEB nuclear translocation, thus increasing PD-L1 and PD-L2 expression to foster an immunosuppressive tumor microenvironment, which mediates immune evasion and drug resistance." (PMID 34091590, 2021).
tumor (continued). "Knockdown of TFEB in macrophages has dramatically increased tumor growth with enhanced infiltration of M2-like macrophages and angiogenesis of tumors." (PMID 33803301, 2021). "CQ resets tumor-associated M2 macrophages to the tumor-inhibiting M1 phenotype in B16 melanoma and H22 hepatocarcinoma mouse tumor models, and ameliorates the immunosuppressive tumor immune microenvironment through a lysosomal calcium-TFEB pathway." (PMID 33718194, 2021). "We cultured OC cell lines and performed cell transfection and assays as well as analytical, fluorescence microscopy, and immunohistochemical techniques to explore a novel function of TFEB in remodeling the tumor immune microenvironment in OC." (PMID 34091590, 2021). "As the role of TFEB in tumor growth is complex and dependent on the tumor type, we evaluated the functions of this transcription factor in the PDAC growth." (PMID 33513833, 2021). "To examine the effects of TFEB on tumor growth, we subcutaneously injected 8988T cells infected with shRNAs against GFP or TFEB into mice to construct a xenograft mouse model." (PMID 33513833, 2021). "Of note, TFEB-overexpressing xenograft tumors exhibited an increase in tumor weight and volume, while knocked-down TFEB expression resulted in slower growth in xenograft tumors." (PMID 33732651, 2021). "CDDP enhanced the expression of TFEB and PD-L1 in tumor tissues, compared with the control group, indicating the significance of TFEB-PD-L1 axis in vivo during tumor growth." (PMID 34091590, 2021). "In the TFEB knockdown xenograft tumor groups, ABCA2 protein expression was decreased, while an increased expression was observed in TFEB-overexpressing xenograft tumor groups compared to vector groups." (PMID 33732651, 2021). "In conclusion, we explored a novel function of TFEB in remodeling the tumor immune microenvironment in OC." (PMID 34091590, 2021). "We also found that CDDP treatment induced TFEB nuclear translocation, thus increasing PD-L1 and PD-L2 expression to foster an immunosuppressive tumor microenvironment, which mediates tumor immune evasion and drug resistance." (PMID 34091590, 2021). "This indicated that TFE3 can be at least another potent tumour promotor beyond TFEB in specific tumour types such as ccRCC." (PMID 33145941, 2020). "In summary, it is indicated that TFE3, like TFEB, is also a potent tumour promotor based on its significant proliferative effect." (PMID 33145941, 2020). "Other than regulating cancer cell-autonomous responses, recent findings indicate that TFEB participates in the regulation of cellular functions of the tumor microenvironment." (PMID 33252196, 2020). "Here, we review the emerging role of TFEB in regulating cancer cell behavior and choreographing tumor-microenvironment interaction." (PMID 33252196, 2020). "In a broader context, the proposed model suggests a novel mechanism by which the loss of signaling through ZKSCAN, TFEB, and FOXO1 results in activation of the autophagy-lysosome pathway in tumor suppression." (PMID 32178401, 2020). "We also found that the basal expression of TFE3 is higher than that of TFEB in ccRCC specimens and tumour cell lines by TCGA and Cancer Cell Line Encyclopedia (CCLE) database." (PMID 33145941, 2020). "Given the role of TGF-β in stimulating TFEB-regulated autophagy in PC, we next examined the potential function of TFEB in TGF-β involving tumor biological behavior." (PMID 31387632, 2019). "Although reduced TFEB expression was identified driving by secreted TGF-β in tumor-associated macrophages, we showed that treatment of TGF-β up-regulates TFEB in Smad4-positive PC cells." (PMID 31387632, 2019). "Tumor bearing mice hearts show increased expression and nuclear localization of TFEB and FoxO3a transcription factors, which are involved in the upregulation of muscle atrophy genes, lysosomal biogenesis genes and autophagy genes." (PMID 29618792, 2018).
tumor (continued). "Time-lapse fluorescence microscopy revealed that these drugs induced a rapid nuclear translocation of TFEB in both tumor cell lines, which was evident as early as 90 min after drug exposure, and further increased during the following hours of incubation." (PMID 30546014, 2018). "It is interesting to note that mTOR, TFEB, and molecules involved in intracellular protein trafficking such as Sec22b are found in tumor-derived MVs." (PMID 28993771, 2017). "To study the mechanisms underlying tumor development in TFEB-fusion RCC, we generated a transgenic mice that specifically overexpress TFEB in the kidney." (PMID 27668431, 2016). "A marked curve shift towards higher transcript levels, compared to the full list of genes, was observed, indicating that the high TFEB level observed in the tumor also increased expression of the reported target genes." (PMID 26654961, 2015). "This tumour harbours translocations involving the transcription factor EB (TFEB) and Alpha (the latter also known as MALATI)." (PMID 24877033, 2014). "Moreover, in tumor cells, the reduction of methylation of key transcription factors (FoxO and TFEB) decreases autophagy activity, further exacerbates the dysfunction of sugar uptake, and promotes tumor growth." (PMID 41522193, 2026). "All FLCN‐mutated tumours, including the sporadic ones and those with somatic FLCN mutations, appear to consistently and diffusely express GPNMB on IHC, which is reflective of the underlying mTORC1 dysregulation, leading to TFEB activation." (PMID 41384711, 2026). "We carried out a limiting dilution assay, the gold standard of CSC evaluation, to determine whether TFEB KD affects tumor-initiating capacity in vivo." (PMID 39814550, 2025). "Moreover, we described how autophagy activation, due to TFEB overexpression, plays a critical role in cilia disassembly, favoring tumor growth in CCA." (PMID 40189703, 2025). "Despite finding that the HLF/TFEB axis drives immune evasion via PD-L1, the regulation of HLF/TFEB axis on tumor immunity may have other mechanisms." (PMID 40779629, 2025). "For example, the HLF/TFEB axis–mediated autophagy may not only support tumor cell survival and proliferation but also alter tumor antigen presentation, immune cell trafficking, and effector immune cell function in the tumor microenvironment (TME)." (PMID 40779629, 2025). "In children and adolescents, a significant fraction of RCCs were historically unclassified, but many of these have since been identified as translocation carcinomas involving TFE3/TFEB or as renal medullary carcinoma (a rare tumor almost exclusive to patients with sickle cell trait)." (PMID 41426798, 2025). "This modification enhances TFEB's role in promoting autophagy, with implications for cancer, where increased TFEB lactylation may contribute to elevated autophagic activity in tumor cells." (PMID 40535811, 2025). "Indeed, TFEB knockdown (KD) inhibited mammosphere formation in vitro and tumor initiation/growth in vivo." (PMID 39814550, 2025). "Furthermore, acetylation of TFEB enhances its stability and nuclear activity, sustaining autophagic flux despite mTORC1 repression, which promotes tumor growth and metastasis." (PMID 41213956, 2025). "Notably, pharmacological activation of TFEB restores lysosomal function and mitigates the metastatic phenotype, highlighting the role of the PTEN-TFEB-Lysosome-EV axis in tumor progression." (PMID 40877546, 2025). "TFEB is an important regulator of macrophage polarization in the tumor microenvironment." (PMID 38287113, 2024). "In this study, we found high abundance of circRHCG in TNBC-derived exosomes, and exosomal circRHCG promoted M2 polarization via enhancing BTRC-dependent ubiquitination and degradation of TFEB, thus facilitating tumor cell metastasis and accelerating TNBC progression." (PMID 38287113, 2024). "Also, TC treatment markedly decreased the protein levels of NF-κB and TFEB in tumor tissues compared to the ADR-treated group." (PMID 39364046, 2024).